INS (insulin)
Diseases named in the same sentence as INS in open-access papers (continued):
Sharing a sentence is not in itself a finding about the gene and the disease.
Hyperglycemia (continued). "A long-standing question in pancreatic islet biology is how glucagon, produced in α-cells in response to low glucose levels, influences insulin secretion from β-cells that occurs in states of hyperglycemia." (PMID 29740399, 2018). "We examined the effect of C. maxima pulp besides insulin on control of hyperglycemia in diabetic patients admitted to Intensive care unit (ICU)." (PMID 30023337, 2018). "It is characterized by increased hyperglycemia resulting from defective production or action of insulin, leading to several complications such as cardiovascular, renal, neurological, and ocular disorders." (PMID 30008637, 2018). "Sulfonylureas have been widely used as insulin secretagogues to reduce hyperglycemia in human diabetic patients, as well as research animals." (PMID 30510962, 2018). "Body weight reduction, water intake increasing, hyperglycemia, and insulin level reduction were considered to be the typical characteristics of the diabetic pathophysiology." (PMID 29853958, 2018). "Alpha-2 adrenoceptor agonist-related hyperglycaemia is known to result from a reduction of insulin release by a direct action of the α-2 adrenoceptor agonist on pancreatic β-cells." (PMID 29743097, 2018). "The results of the present study revealed that STZ treatment significantly reduced body weight, induced hyperglycemia and reduced circulating insulin levels indicating the establishment of type 2 DM." (PMID 30041644, 2018). "Reduced insulin-stimulated glucose uptake further contributes to hyperglycemia, overburdening the β-cells, which have to produce additional insulin in response." (PMID 30373146, 2018). "Among peripheral CB1Rs, activation of the hepatic CB1R induces ER stress-dependent hepatic insulin resistance and gluconeogenesis, resulting in hyperglycemia." (PMID 29570673, 2018). "After feeding, insulin stimulates liver to take more glucose from the blood and synthesize glycogen, thus reducing the postprandial hyperglycemia." (PMID 30140027, 2018). "Vatinoxan was able to alleviate the romifidine induced hyperglycaemia despite of the wide variation in baseline insulin concentrations." (PMID 29743097, 2018). "Most importantly, high-dosed d-serine supplementation resulted in reversible hyperglycemia and glucose intolerance within one to two weeks of supplementation due to impaired insulin secretion." (PMID 30093356, 2018). "Romifidine induced hyperglycaemia in horses is similar to other α-2 adrenoceptor agonists, but its effects on serum insulin warrant further investigations." (PMID 29743097, 2018). "Constitutive activation of liver PKA-dependent signaling stimulates gluconeogenesis, leading to hyperglycemia, which would be expected to stimulate insulin secretion from β-cells." (PMID 29740399, 2018). "Two other studies compared the neutral protamine Hagedorn (NPH) insulin to glargine, both in a basal-bolus protocol, for treatment of steroid-induced hyperglycemia in hospitalized patients." (PMID 30373567, 2018). "These were indicated by hyperglycemia, increased serum hemoglobin A1c level and decreased insulin secretion, inhibition of liver glycogen synthase (LGS), and hepatic glycogen synthesis." (PMID 29437243, 2018). "Currently, treatment of hyperglycemia in preterm infants is highly variable and controversial and involves restricting glucose infusion and/or insulin therapy." (PMID 29544513, 2018). "As for insulin, hyperglycemia is the stimulus for increased insulin secretion to enhance cell glucose uptake." (PMID 30149518, 2018). "Postoperative hyperglycaemia is an important component of post-operative complications and delayed recovery and arises as a result of decreased insulin-stimulated whole-body glucose disposal as well as increased endogenous glucose release." (PMID 29129636, 2018).
Hyperglycemia (continued). "Butyrate supplementation to obese, prediabetic mice significantly improved the intestinal epithelial barrier and insulin secretion from beta cells and decreased body adiposity as well as weight gain, insulin resistance, hyperinsulinemia, and hyperglycemia." (PMID 29082264, 2017). "In STZ-induced diabetic mice, dietary intake of genistein significantly improved hyperglycemia, glucose tolerance, and circulating insulin levels, preserving islet β-cell proliferation, survival, and mass." (PMID 28574454, 2017). "Overall, there do not appear to be any major important differences in effects on hypoglycemia, hyperglycemia, weight or long-term safety between the three available RAIs among insulin-naive individuals with T2DM in clinical practice." (PMID 28702259, 2017). "Normal insulin secretion raises β cell ER stress, but when blood glucose rises too high, or the hyperglycemia is too prolonged, so called “glucotoxicity” further enhances β cell ER stress." (PMID 29033899, 2017). "The first part of AUC represented the glucose metabolism by insulin secretion capacity and insulin sensitivity at hyperglycemia whereas the second part of AUC was mainly explained by insulin sensitivity." (PMID 29151980, 2017). "Incretins, especially glucagon-like peptide 1 (GLP-1) secreted by intestinal L-cells, are a group of metabolic hormones that inhibit postprandial hyperglycemia by increasing the amount of insulin released from pancreatic beta cells." (PMID 28538869, 2017). "FMO3 is activated by insulin, and knockout in insulin resistant mice prevents hyperglycemia, hyperlipidemia, and atherosclerosis." (PMID 28134761, 2017). "After initiation of treatment with basal insulin, which decreases fasting glucose, the relative contribution of postprandial hyperglycemia to total hyperglycemia increases from 20–24% to 59–69%." (PMID 28115994, 2017). "Hyperglycemia is a common problem in critically ill patients, especially with severe stress, steroid use, and diabetes mellitus, requiring treatment with insulin." (PMID 29308073, 2017). "After 12-week saxagliptin treatment in high-fat diet/streptozotocin-induced diabetic rats, significant improvement in pancreas insulin secretion capacity evaluated by hyperglycemia clamp and increased β-cell to α-cell areas ratio were observed." (PMID 29230196, 2017). "The hyperglycemia: intensive insulin infusion in infarction (HI-5) study was a prospective randomized-controlled trial investigating the effect of intensive insulin therapy on mortality in patients with an acute myocardial infarction." (PMID 29233143, 2017). "Pre-exposure to low-dose insulin enhanced hyperglycemia-induced endogenous insulin and c-peptide secretion in both groups." (PMID 28497374, 2017). "The NDF25 and NDF35 groups with 75.7 and 64.4% serum insulin respectively presented relatively normoglycemia, whereas the FDF35 (85.75% serum insulin) were notably hyperglycaemia (>300 mg/dL)." (PMID 28129400, 2017). "In a prospective observational study, we measured c-peptide as a biomarker of endogenous insulin secretion during moderate permissive hyperglycemia in critically ill adult patients with T2DM." (PMID 28497374, 2017). "In this study, we observed that the Sit Less regimen improved insulin sensitivity, mean 24 h glucose levels, 24 h glucose excursions, duration of hyperglycaemia (blood glucose ≥10 mmol/l) and fasting triacylglycerol levels." (PMID 27904925, 2017). "In contrast to our guinea-pig model, the use of STZ to establish insulin-dependent hyperglycemia in mice and rats is well established." (PMID 28093504, 2017). "For example, with even modest hyperglycemia the first phase insulin response to glucose is completely shut off in essentially every beta cell." (PMID 28174593, 2017). "Its landmark is hyperglycemia, secondary to an altered insulin production by ß cells of the pancreatic islets, a disability of body cells to properly respond to insulin or both." (PMID 29200427, 2017).
Hyperglycemia (continued). "A previous report showed that male CRF-OE had elevated plasma insulin levels and hyperglycemia consistent with our observations." (PMID 28101317, 2017). "Such regulation is particularly complex in the transition from fasting to postprandial state on which its secretion must be tightly adjusted to insulin needs, so tissue glucose supply is assured while hypo- and hyperglycaemia are prevented." (PMID 28286777, 2017). "Although it has long been known that the multifaceted acute stress response is a key determinant of hyperglycemia in the critically ill, the Leuven trial from 2001 suggested that decreasing glucose levels with insulin administration improved outcome." (PMID 28826408, 2017). "The resulting metabolic disorders are characterized by hyperglycemia resulting from defects in insulin secretion and/or insulin action and by altered metabolism of lipids, carbohydrates, and proteins." (PMID 29479371, 2017). "Both in humans and in rodents, exendin 9–39 efficiently blocks the effect of GLP-1 on insulin secretion and it has even been shown to induce hyperglycemia despite a compensatory increase in endogenous GLP-1 levels." (PMID 29206860, 2017). "Collectively, these data support that glucocorticoids excess itself in CRF-OE is responsible for the elevated circulating levels of leptin and insulin and the hyperglycemia." (PMID 28101317, 2017). "In advanced state of uncontrolled T2DM patients, there is impaired pancreatic β-cell function, and diminished insulin sensitivity in the insulin responsive tissues including the heart, leading to hypoinsulinemia and hyperglycemia." (PMID 28923829, 2017). "Accordingly, the model generated displayed hyperglycaemia and hyperinsulinemia, as basal glucose and insulin levels under fast and fed conditions were significantly increased in blood of HFD mice compared with LFD mice (respectively)." (PMID 28244645, 2017). "This relationship demands adjustment in treatment and the need to employ insulin in the treatment of hyperglycemia during active TB infection when required." (PMID 29270319, 2017). "Under postprandial hyperglycemia, insulin-stimulated glucose uptake by skeletal muscle increases; non-insulin- mediated glucose uptake also increases in skeletal muscle but not in the central nervous system." (PMID 29206848, 2017). "For that reason, the development of frank hyperglycaemia in this study was accomplished in insulin-resistant FDF-fed rats using a single low dose of STZ." (PMID 28129400, 2017). "Further evidence that fructose consumption reduces hepatic insulin sensitivity and induces hyperglycemia comes from studies where hepatic fructose uptake was prevented." (PMID 28926951, 2017). "Such physiological profiles are incongruous with high insulin sensitivity at night, or rising prerequisites at dawn with resulting consequences of nocturnal hypoglycaemia and pre-breakfast hyperglycaemia." (PMID 28779138, 2017). "Hyperglycemia in these cases is a result of low insulin secretion in the milieu of maternal normoglycemia due to increased set point stimulated insulin secretion." (PMID 28663157, 2017). "NAC beta oscillatory power is enhanced by hyperglycemia and can be induced by direct insulin application into the central nervous system." (PMID 29138510, 2017). "In obese and diabetic women, tissues involved in insulin-mediated glucose uptake (such as the liver) become insulin resistant, leading to hyperglycaemia and hyperinsulinaemia." (PMID 29299023, 2017). "In vitro studies of the impact of insulin on the nerve action potential under normal or high glucose conditions have found that hyperglycemia prolongs the action potential, an effect that is abolished by insulin." (PMID 28191471, 2017). "Context: Neonatal diabetes mellitus, a rare condition occurring in approximately 1 in 500 000 live births, is defined as insulin-requiring hyperglycemia presenting in the first months of life." (PMID 28540314, 2017).
Hyperglycemia (continued). "Hyperglycemia and abnormal insulin signaling enhance the production of advanced glycation end-products (AGES) and of their receptors (RAGE) in the heart." (PMID 28781721, 2017). "Third, experimental studies determined that induced hypokalemia led to declines in insulin release in response to hyperglycemia and to a decrease in pancreatic β-cell sensitivity to hyperglycemia with a reduction in insulin release." (PMID 28346526, 2017). "Consistent with previous observations hyperglycemia decreased Akt phosphorylation suggesting that this pathway plays a key role in the inhibitory effect of hyperglycemia on insulin-induced preservation of myocardial contractility after ischemia." (PMID 28376800, 2017). "Subjects with pre-T1D subjects have been found to have diminished first phase insulin responses in response to glucose shortly before obvious hyperglycemia develops." (PMID 28174593, 2017). "In simple correlation, indices of hyperglycemia moderately correlate with index of insulin secretion, but weakly correlate with indices of insulin sensitivity." (PMID 28878826, 2017). "It was observed that the FDF-fed group treated STZ (35 mg/kg bw) had a 12.2% decrease in serum c-peptide which consequently resulted in 85.8% available circulatory serum insulin and frank hyperglycaemia." (PMID 28129400, 2017). "This was most striking for ‘hyperglycaemia’, where the definition varied between ‘total insulin dose’ blood glucose >150 mg/dl on any day, an increase of >200 mg/dl and others, hence its exclusion as an outcome." (PMID 28351429, 2017). "When the pancreatic β-cells fail to secrete sufficient insulin to overcome insulin resistance, hyperglycemia becomes evident." (PMID 28387741, 2017). "Patients treated with adjunctive dexamethasone did not experience a higher rate of dexamethasone-related complications such as hyperglycemia requiring insulin, gastric bleeding, and herpes simplex infection." (PMID 27613024, 2017). "In the present study, pharmacotherapy (use of insulin or metformin) for management of hyperglycemia in pregnancy was strong predictor of progression to abnormal glucose tolerance at 6–12 weeks postpartum (OR 3.14; 95% CI; 1.20–8.21)." (PMID 28491872, 2017). "Reduction in insulin levels results from destruction of β-cells in T1DM, which is directly linked with hyperglycemia and associated complications." (PMID 28878669, 2017). "Continuous hyperglycemia is necessary in this model, so that the islets are constantly stimulated for permanent maximal insulin synthesis and secretion." (PMID 29262643, 2017). "Similar to what is observed in humans with type 1 diabetes, NOD mice suffer from infiltration of dendritic cells and macrophages in pancreatic islets leading to inflammation, hyperglycemia, and apoptosis of insulin-producing β cells [21, 22, 23•]." (PMID 28836097, 2017). "Such transient hyperglycaemia after cessation of HI-infusion has been attributed to suppressed endogenous insulin production." (PMID 28421113, 2017). "Insulin-dependent GLUT4 is responsible for insulin-regulated glucose uptake into fat and muscle cells to prevent hyperglycemia." (PMID 28241483, 2017). "Acute hyperglycemia diminishes the cardioprotective effects of insulin preconditioning in the isolated rat heart, possibly mediated through the suppression of myocardial Akt phosphorylation." (PMID 28376800, 2017). "The model has been characterized with insulin resistance and development of hyperglycaemia in the presence of significant high level of insulin." (PMID 29019956, 2017). "Cyanidin and its derivatives also suppress hyperglycemia and improve glucose homeostasis and insulin sensitivity." (PMID 28788070, 2017). "In contrast, SE leaf extract at the administered doses (400 and 800 mg/kg BW) significantly lowered STZ-induced hyperglycemia, improved insulin and glycogen contents in extract-treated rats compared to diabetic control animals." (PMID 29216879, 2017).
Hyperglycemia (continued). "T2DM is characterized by hyperglycemia resulting from impaired insulin secretion, defects in insulin action, increased hepatic glucose production, and decreased peripheral glucose utilization." (PMID 29062839, 2017). "SGLT2 inhibitors are a new class of oral antidiabetic drugs, which act by reducing hyperglycemia by promoting urinary glucose excretion independently of the secretion or action of insulin." (PMID 28938561, 2017). "This animal model of diet-induced prediabetes shows reduced glucose tolerance, postprandial hyperglycemia, hyperinsulinemia, reduced insulin sensitivity (resistance), and hypertriglyceridemia, together with impaired gluconeogenesis and lipogenesis." (PMID 28635632, 2017). "In monkeys, pancreatectomy at various ages between 6 and 15 years resulted in insulin dependency and hyperglycemia, which was then deliberately uncontrolled." (PMID 28836097, 2017). "Animals were grouped based on their 6-week (initial) weights to determine the influence of early weight on subsequent weight gain, insulin levels, glucose tolerance and hyperglycemia." (PMID 28640904, 2017). "In the past, PHT was reported to be related to hyperglycemia and reduced insulin response in patients with glucose intolerance." (PMID 28239528, 2017). "Resveratrol reduces insulin secretion and thus decreases ATP content and protects the diabetic pancreas from hyperglycemia." (PMID 29018489, 2017). "The resulting differentiated cells express insulin at both the mRNA and protein level, and ameliorate hyperglycaemia in STZ rats." (PMID 28279194, 2017). "The development of HCC is thought to be related to the proliferative effects of insulin and insulin-like growth factor 1, oncogenic effects of hyperglycemia, and inflammatory effects of obesity." (PMID 29379799, 2017). "On resolution of DKA and cessation of intravenous insulin infusion, rebound hyperglycaemia is a major issue." (PMID 28659865, 2017). "High doses of salicylates reversed hyperglycemia, hyperinsulinemia, and dyslipidemia in insulin resistant Zucker fa/fa obese rats by sensitising insulin signalling." (PMID 28586387, 2017). "Streptozotocin selectively damages insulin-producing pancreatic endocrine cells and can induce experimental hyperglycemia." (PMID 29270392, 2017). "In recent years, an increasing number of studies have demonstrated that SOCS3 and STAT3 mediate inflammation, apoptosis, and insulin signalling in hyperglycaemia-stimulated retinal endothelial cells." (PMID 29318137, 2017). "There were two instances of hyperglycaemia relapse during CIDP flare-ups that required insulin therapy and remitted after i.v. immunoglobulin (IVIG) therapy improving neurological symptoms." (PMID 28835984, 2017). "In this context, the ability of insulin to acutely regulate hepatic gluconeogenesis and prevent hyperglycemia occurs mostly by an indirect mechanism through inhibition of white adipose tissue lipolysis." (PMID 28993702, 2017). "Genetic ablation of Plin2 in Akita mice led to significant amelioration of hyperglycemia, decreased β cell apoptosis, and partially restored β cell mass and pancreatic insulin content." (PMID 28102311, 2017). "Insulin treatment of women with GDM (i.e., patients under insulin therapy) reverses the GDM-associated maternal and foetal hyperglycaemia and the increase in IRS-1 and PI3K p85α activity caused by this disease to values in normal pregnancies." (PMID 29104874, 2017). "Sprague-Dawley rats were subjected to doses of tacrolimus and sirolimus that reliably induce hyperglycemia and an insulin-resistant state." (PMID 28860611, 2017). "The injection of insulin for hyperglycemia should be cautious in case of hypoglycemia on account of decreased hepatic insulin sensitivity, enhanced peripheral insulin sensitivity and subsequently decreased secretion of glucagon." (PMID 29212278, 2017). "DM is a metabolic disease characterized by hyperglycemia resulting from defects in insulin secretion, insulin action or both." (PMID 29141668, 2017).